SPSB4 (splA/ryanodine receptor domain and SOCS box containing 4)
Description:
Substrate recognition component of a SCF-like ECS (Elongin BC-CUL2/5-SOCS-box protein) E3 ubiquitin-protein ligase complex which mediates the ubiquitination and subsequent proteasomal degradation of target proteins. Negatively regulates nitric oxide (NO) production and limits cellular toxicity in activated macrophages by mediating the ubiquitination and proteasomal degradation of NOS2. Acts as a bridge which links NOS2 with the ECS E3 ubiquitin ligase complex components ELOC and CUL5. Diminishes EphB2-dependent cell repulsive responses by mediating the ubiquitination and degradation of EphB2/CTF2. Regulates cellular clock function by mediating the ubiquitin/proteasome-dependent degradation of the circadian transcriptional repressor NR1D1.
Synonyms: SSB-4; SSB4
Tractability: PROTAC: ubiquitination databases record sites on it.
Gene: Protein-coding gene on chromosome 3 (141,050,744 to 141,148,613, forward strand). Ensembl gene ENSG00000175093.
Subcellular location: Cytoplasm; Cytoplasm, cytosol
Subcellular location (Human Protein Atlas): Golgi apparatus; Nucleoplasm
Pathways (Reactome):
Immune System: Antigen processing: Ubiquitination & Proteasome degradation
Metabolism of proteins: Neddylation
Gene Ontology:
Molecular function: protein binding; ubiquitin-like ligase-substrate adaptor activity
Biological process: positive regulation of protein polyubiquitination; protein ubiquitination; regulation of circadian rhythm; ubiquitin-dependent protein catabolic process; proteasome-mediated ubiquitin-dependent protein catabolic process; intracellular signal transduction
Cellular component: cytosol; SCF ubiquitin ligase complex; cytoplasm
Genetic constraint (gnomAD): Loss-of-function variants: 21 observed, 14.68 expected, observed/expected ratio (o/e) 1.43, 90% interval 1 to 1.89. The synonymous counts are far from expectation, so gnomAD's model fits this gene poorly and the ratio says little. Missense variants: 399 observed, 337.28 expected, observed/expected ratio (o/e) 1.18, 90% interval 1.09 to 1.28. Synonymous variants: 207 observed, 154.84 expected, observed/expected ratio (o/e) 1.34, 90% interval 1.19 to 1.5.
Homologues: Orthologues: chimpanzee SPSB4 (100% identical), macaque SPSB4 (99% identical), mouse Spsb4 (98% identical), guinea pig SPSB4 (97% identical), pig SPSB4 (97% identical), dog SPSB4 (97% identical), rat Spsb4 (86% identical), tropical clawed frog spsb4 (81% identical), zebrafish spsb4b (69% identical), Drosophila melanogaster gus (69% identical), Caenorhabditis elegans spsb-1 (51% identical), Caenorhabditis elegans spsb-2 (43% identical). Paralogues in human: SPSB1 (75% identical), SPSB2 (51% identical), FBXO45 (34% identical), SPSB3 (23% identical).
Diseases named in the same sentence as SPSB4 in open-access papers:
SPSB4 is named in the same sentence as 11 diseases in open-access papers, as found by Europe PMC text mining. Sharing a sentence is not in itself a finding about the gene and the disease. The quoted sentences say what the papers report.
pancreatic cancers (2 papers, 2020 to 2021). "SPSB4 was identified among five genes, ADAMTS2, HOXA1, PCDH10, SEMA5A and SPSB4, that were highly/frequently methylated in liquid biopsies of pancreatic cancers although with a relatively low potential compared with the other four markers." (PMID 34062897, 2021). "In tissue samples, SPSB4 was identified as a potential DNA methylation marker of pancreatic cancer with the highest AUC (area under the receiver operating characteristic curve)." (PMID 34062897, 2021). "Of the three criteria, we identified eight genes that were the most highly/frequently methylated in pancreatic cancers (PCDH10, SPSB4, HOXA1, ADAMTS2, BMP3, C13orf18, CCND2, and SEMA5A)." (PMID 32520974, 2020).
autism (1 paper, 2022). Persistent deficits in social interaction and communication and interaction as well as a markedly restricted repertoire of activity and interest as well as repetitive patterns of behavior. "Cg04112471 is annotated to SPSB4 (SplA/Ryanodine Receptor Domain And SOCS Box Containing 4), a gene regulating EphB2-dependent cell repulsive responses that has also been associated with autism." (PMID 33494854, 2022).
autism spectrum disorder (1 paper, 2022). A spectrum of developmental disorders that includes autism, and Asperger syndrome. "Interestingly, both APCDD1 and SPSB4 have previously been linked to autism spectrum disorder in clinical settings." (PMID 33494854, 2022). "For example, SPSB4 was found to be similarly hypomethylated in a cross-sectional study of 131 children (age 3–12 years) diagnosed with autism spectrum disorders versus controls." (PMID 33494854, 2022).
COVID-19 (1 paper, 2024). A disease caused by infection with severe acute respiratory syndrome coronavirus 2. "The AUC values for these genes in depression patients surpassed 0.8, and those in COVID-19 patients exceeded 0.7, with the exception of COL10A1, SPSB4, and SLC10A2, whose AUC values were less than 0.7." (PMID 39588145, 2024).
glioma (1 paper, 2021). A benign or malignant brain and spinal cord tumor that arises from glial cells (astrocytes, oligodendrocytes, ependymal cells). "SPSB4 (a SPRY domain-containing SOCS box protein) is enriched in gliomas and testis cancer tissues and is a favorable prognostic marker in gliomas." (PMID 34062897, 2021).
cancer (2 papers, 2020 to 2021). A tumor composed of atypical neoplastic, often pleomorphic cells that invade other tissues. "We found that Cercam and Spsb4, identified as prognostic markers in a few cancer types, are associated with downregulated geromiRs and are upregulated in the TME cells." (PMID 34062897, 2021).
SPSB4 also shares sentences with these, for which no sentence is quoted: chronic pancreatitis (1 paper); depression (1); Sepsis (1); Stroke (1); testis cancer (1).